PPARG (peroxisome proliferator activated receptor gamma)
Diseases named in the same sentence as PPARG in open-access papers (continued):
Sharing a sentence is not in itself a finding about the gene and the disease.
bacterial infection (14 papers, 2012 to 2023). "Thus, not only host defense but also bacteria themselves can engage PPARγ for its anti-inflammatory functions during pathogenic bacterial infections." (PMID 27774097, 2016). "As ROS production was more pronounced in PPARγ-deficient macrophages already early during bacterial infection this may explain the improved subsequent early control of intracellular bacterial growth." (PMID 22629382, 2012). "Hence, PPARγ activation aimed at strengthening the immune response and immunomodulation could be used as an alternative antimicrobial strategy to avoid bacterial infections in burn patients predisposed to infectious complications." (PMID 36361535, 2022). "Because PPARγ has been shown to regulate IL-10 production during bacterial infection, we found that cadmium exposure and S. pneumoniae infection reduced IL-10 levels in the Pparfl/fl mice, and the PpargΔM mice showed an even greater reduction." (PMID 36928191, 2023). "In conclusion, PPARγ activation by pioglitazone prevents clinical deterioration due to post-burn bacterial infection and improves survival." (PMID 36361535, 2022). "PPARγ activation triggers apoptosis in a variety of leukocytes, which can dampen the host immune response during bacterial infections." (PMID 27774097, 2016). "We have here reviewed research investigating the effects of PPARγ activation or inhibition during bacterial infections." (PMID 27774097, 2016). "In this review we discuss the role of PPARγ and its activation during bacterial infections, with focus on the potential of PPARγ agonists and perhaps antagonists as novel therapeutic modalities." (PMID 27774097, 2016). "The positive effect of PPARγ (and/or its ligands) in bacterial infections, especially its anti-inflammatory effects via inhibition of proinflammatory molecules such as IL-6, TNF-α, IL-1β, and IL-12, has been well documented." (PMID 27774097, 2016). "Regardless, in bacterial infections where optimal pathogen clearance and prevention of excessive inflammation are equally critical for the health and survival of patients, PPARγ agonists offer new therapeutic strategies." (PMID 27774097, 2016). "Pharmacological stimulation of PPARγ has been shown to lead to an increased occurrence of bacterial infections in patients, suggesting that PPARγ plays a key role in anti-bacterial defense." (PMID 22629382, 2012). "Controversy exists regarding the role of PPARγ in bacterial infections." (PMID 36928191, 2023). "In this study, we investigated whether the administration of a PPARγ agonist could modulate the Kupffer cell phenotype and thereby ameliorate the dysregulated innate response during post-burn bacterial infection." (PMID 36361535, 2022). "When it comes to bacterial infection, PPARγ activation appears to correlate with poor outcome." (PMID 35003101, 2021). "PPARγ can also negatively affect hosts' response to bacterial infections by other mechanisms." (PMID 27774097, 2016). "In this review, we discuss the role of PPARγ specifically in bacterial infections." (PMID 27774097, 2016). "Despite this caveat, however, this group of studies suggests that PPARγ may adversely affect the host's ability to combat bacterial infections." (PMID 27774097, 2016). "As we observed improved bacterial clearance in LysM- PPARγKO mice we next investigated the influence of PPARγ on molecular mechanisms known to be critical for control of bacterial infection, such as phagocytosis and generation of listeriocidal mediators like reactive NO and ROS." (PMID 22629382, 2012). "Innate immune defense against bacterial infection appears to be compromised by PPARγ." (PMID 22629382, 2012). "Pharmacological interference with PPARγ activity in myeloid cells might represent a novel strategy to overcome intracellular bacterial infection." (PMID 22629382, 2012).
bacterial infection (continued). "Thus, this study investigated whether the PPARγ agonist, pioglitazone, can protect against post-burn bacterial infection and determined the effects of PPARγ activation in mouse models." (PMID 36361535, 2022). "Impaired adipogenesis induced by the PPARγ inhibitors GW9662 and BADGE results in an increased bacterial infection in the skin and colon." (PMID 35324426, 2022). "While P. aeruginosa infection increased PPARγ activity, CSE greatly reduced PPARγ activity even in the presence of bacterial infection." (PMID 30877402, 2019). "Anti-inflammatory effects of PPARγ activation are not confined to bacterial infections of the lungs." (PMID 27774097, 2016). "The negative effect of PPARγ activation during bacterial infections is supported by a systematic review and meta-analysis of 13 long-term randomized controlled trials of TZDs that involved 17,627 participants (8,163 receiving TZDs and 9,464 receiving control drugs)." (PMID 27774097, 2016). "However, there is no study on the relevance of PPARγ in myeloid cells for the outcome of bacterial infection, although it is clear that myeloid cells are the key cell population in anti-bacterial defense." (PMID 22629382, 2012).
adenocarcinoma (13 papers, 2000 to 2022). A common cancer characterized by the presence of malignant glandular cells. "However, because it has been reported that OE33-derived transplantable adenocarcinoma was enhanced in vivo by systemic PPARγ activation due to cell proliferation, the detailed role of PPARγ in the esophagus remains controversial." (PMID 20885923, 2010). "PPARγ activation also induces conversion of adenocarcinoma cells to a more differentiated phenotype with polarity, which is associated with normal epithelial cells." (PMID 27698657, 2016). "PPARG mRNA is detected in the normal human mucosa of the caecum and colon, as well as in adenocarcinomas and CRC-derived cell lines." (PMID 22991505, 2012). "Immunohistochemistry was used to demonstrate the presence of PPARγ protein in surgically resected specimens from well differentiated, moderately differentiated and poorly differentiated adenocarcinoma." (PMID 11044367, 2000). "In this study, lung A549 and breast MCF-7 adenocarcinoma cells were morphologically changed into adipocyte-like cells with adiposomes in the only DEX-containing culture medium and resulted in up-regulated GLUT4 and PPARγ expression." (PMID 33456717, 2020).
brain diseases (12 papers, 2008 to 2023). "Increasing evidence has demonstrated the PPARγ agonistic property of TEL in several brain disorders." (PMID 35553009, 2022). "Peroxisome proliferation-activated receptor gamma (PPARγ) has many functions, including immune response regulation, energy metabolism, and mitochondrial functions and PPARγ agonists may exert neuroprotective effects in brain disorders." (PMID 31798583, 2019). "PGC-1α activation regulates expression of genes that stimulate mitochondrial biogenesis and neuroinflammation; therefore, targeting transcription factors of PPARγ and PGC-1α may be beneficial in the treatment of brain diseases." (PMID 31798583, 2019).
infectious disease (12 papers, 2008 to 2025). A disorder directly resulting from the presence and activity of a microbial, viral, or parasitic agent in humans. "Use of PPARγ agonists or antagonists to treat infectious diseases must take into account the timing of administration and the pathogen and must balance pro- and anti-inflammatory mechanisms to enable an improved outcome." (PMID 30897154, 2019). "In the current review, we discuss recent findings concerning the role of NRs in infectious diseases with an emphasis on PPARγ and LXR, the two most studied." (PMID 30897154, 2019). "Altogether, these results identify P17 as an original activator of the fungicidal response of macrophages that acts upstream PPARγ/CLRs axis and offer new immunomodulatory therapeutic perspectives in the field of infectious diseases." (PMID 29250064, 2017). "More specifically, we propose that PPARγ is a promising therapeutic target for chronic inflammatory and infectious diseases where Th17 cells contribute to the gut immunopathogenesis." (PMID 23592971, 2013). "In this regard, our work indicates that CFZ is a PPARγ agonist, with a similar binding affinity as TZD, but which is seemingly safe as it is in clinical use for the treatment of infectious diseases." (PMID 38701619, 2024). "Herbal medicine probably controls the infectious disease mainly based on immunomodulatory agents stimulation (such as GSK3B, MAPK14, PPARγ) will probably help innate and adaptive immune, and regulation the inflammatory cytokines and proinflammatory mediators (like IL-6, IL-8, TNF-α, COX2)." (PMID 29301573, 2018).
colonic polyp (10 papers, 2012 to 2024). "It has been reported that PPARγ may provide a molecular link between a high-fat diet and increased risk of colon polyp formation during PPARγ activation." (PMID 23476786, 2013). "In mouse models, an increase in colon polyp incidence after therapy with PPARG agonists was shown." (PMID 38378472, 2024). "Activation of PPARγ increases colonic polyps in the APC+/min mouse model of colon carcinogenesis." (PMID 23516550, 2013). "In the present study, the inhibition of A2AR by the antagonist ligand SCH58261 blocked the effects of inosine on PPARγ signaling activation and mucosal barrier improvements, suggesting that A2AR may be a novel target for the treatment of intestinal disorders." (PMID 33820558, 2021).
heart disease (9 papers, 2010 to 2025). "For this reason, agonists that modulate the activity of PPARa and PPARg have been considered for the treatment of cardiac diseases." (PMID 41511296, 2025). "Much of our understanding of the roles of the PPAR isoforms, PPARα, PPARδ and PPARγ are in metabolic regulation, as they play roles in insulin sensitivity, glucose homeostasis and oxidation of fatty acids and cardiac disease." (PMID 40704293, 2025). "Future studies are required to more precisely clarify regulatory roles of ACE2 and PPARγ as biomarkers of myocardial injury and related heart diseases." (PMID 24067190, 2013). "As the effects of PPARγ on the heart are not fully understood, we and others have examined whether PPARγ is involved in various heart diseases." (PMID 20814542, 2010).
central nervous system diseases (8 papers, 2015 to 2025). "PPARγ agonists have shown promising beneficial effects in several animal models of central nervous system disorders in which an inflammatory component is strongly implicated." (PMID 26016630, 2015). "Peroxisome proliferator‐activated receptor gamma (PPAR‐γ) has been reported to inhibit inflammation and oxidative stress via modulating microglial polarization in various central nervous system diseases." (PMID 39496476, 2024). "It is known that the activation of PPARγ has anti-inflammatory effects that are beneficial in central nervous system diseases presenting inflammatory processes, including ALS." (PMID 31752240, 2019). "Beyond the functions in peripheral systems, PPARγ is also reported as a potential therapeutic target in central nervous system diseases due to its relationship to decreasing pro-inflammatory mediators and improving neurological outcome." (PMID 25889216, 2015). "As a proof-of-concept, in representative efferocytosis-deficit central nervous system disease spinal cord injury model, impaired efferocytosis is reversed by M-P-NP@PPARγ, resulting in neural regeneration and remyelination and ultimately promoting motor function recovery." (PMID 41447482, 2025).
immune disorders (6 papers, 2013 to 2024). "We have shown that the mTOR/PPARγ axis is partly responsible for the acute and chronic (analogous to DEARE) immune dysfunction in burn injury, and experiments are underway to determine if MSC-EV can modulate this response in an mTOR-dependent fashion." (PMID 37404812, 2023).
hematological malignancies (5 papers, 2008 to 2023). "Because PPARγ agonists are being tested as inhibitors of angiogenesis, it is important to understand the role of angiogenesis and associated signal transduction pathways in the progression of hematological malignancies." (PMID 20204067, 2010). "The potential for PPARγ agonists as inhibitors of Stat3 and NF-κB survival signaling in hematological malignancies is discussed in Section 2.8." (PMID 20204067, 2010). "This will require the identification of PPARγ target genes that mediate theantitumorigenic effects in hematological malignancies." (PMID 18528522, 2008). "Here we shall review the antitumor advances of PPARγ, alone and in combination with RARα ligands in control of cell proliferation, differentiation, and apoptosis and their potential therapeutic applications in hematological malignancies." (PMID 22685453, 2012). "In that PPARγ agonists inhibit the IL-6-regulated Stat3 signaling cascade, a role for PPARγ agonists in regulating expression of miRNAs critical to the pathogenesis of hematological malignancies may be an important avenue of future scientific investigations." (PMID 20204067, 2010).
vascular disorder (5 papers, 2014 to 2024). A general term used to describe any disease affecting blood vessels]. "DLL4/NOTCH1/PPARγ agonists and/or PI3K/AKT antagonists are attractive therapeutic targets for preventing or even possibly reversing progressive pathologic vasculopathy in PAH." (PMID 38903104, 2024).
gastrointestinal disease (4 papers, 2010 to 2023). A disease that occurs in the gastrointestinal system, excluding the hepatobiliary system. "The enrichment analysis performed for these GIN-activated genes identified some pathways related to cytokine-mediated immune response and the PPARG signaling pathway as well as disease terms related to inflammation and gastro-intestinal diseases as enriched." (PMID 29703268, 2018). "The network displaying the highest score (gene expression, developmental disorder, gastrointestinal disease; score = 37) shows PPARγ – a master regulator of adipogenesis – as a central gene." (PMID 22384002, 2012).
heart (4 papers, 2004 to 2023). "Peroxisome proliferator-activated receptor γ (PPARγ) agonist rosiglitazone treatment can predispose the heart to failure in human and rodent models." (PMID 29434588, 2018).
proliferative retinopathies (4 papers, 2008 to 2017). "Moreover, acyl-CoA thioesterases are highly regulated by peroxisome proliferator-activated receptors (PPARs), and PPARγ agonists have shown promise as targets in animal models of proliferative retinopathies." (PMID 22390717, 2012). "The currently approved antidiabetic TZD, rosiglitazone (a full PPARγ agonist), and the antihypertensive ARB, telmisartan (a partial PPARγ agonist) have both shown promise in animal models of proliferative retinopathies." (PMID 18509499, 2008).
respiratory diseases (4 papers, 2005 to 2025). "The activation of PPARγ can confer protection against oxidative stress and the inflammatory response in the presence of respiratory diseases and in rodents challenged with chemotherapy." (PMID 36678549, 2022). "PPARγ activation can confer protection against oxidative stress and the inflammatory response in respiratory diseases." (PMID 36678549, 2022). "In addition to Nrf2, peroxisome proliferator-activated receptor gamma (PPARγ) is a ligand-activated transcription factor that can confer protection against oxidative stress and inflammatory response in respiratory diseases." (PMID 36297334, 2022).
autosomal dominant disease (2 papers, 2018 to 2024). Autosomal dominant form of disease. "Variants in PPARG gene (3p25.2; peroxisome proliferator activated receptor gamma) are responsible for type 3 FPLD (MIM: #604367), an autosomal dominant disease." (PMID 29557732, 2018).
genetic disorders (2 papers, 2010 to 2026). "Missense mutations in nuclear receptor (NR) transcription factors cause a number of genetic disorders, including PPARG mutations that result in familial partial lipodystrophy type 3 (FPLD3)." (PMID 41793069, 2026).
hematological cancers (2 papers, 2008 to 2017). "It is important that studiesbe performed to carefully analyze PPARγ levels, as well as the activationstatus of PPARγ in hematological cancers." (PMID 18528522, 2008).
mitochondrial disease (2 papers, 2020 to 2023). "Exogenous compounds, such as AICAR, bezafibrate, and resveratrol, can stimulate mitochondrial biogenesis via activation of the PPARγ/PGC-1α pathway, and thus have been considered as potential leads for mitochondrial disease treatment." (PMID 32244971, 2020).
neurodevelopmental disorder (2 papers, 2022 to 2024). A behavioral and cognitive disorder with onset during the developmental period that involves impaired or aberrant development of intellectual, motor, or social functions. "Th importance of the PPARγ activation and its therapeutic potential in several neurological and neurodevelopmental disorders has already been demonstrated, as PPARγ’s role in mitigating the neuroinflammatory process." (PMID 35563317, 2022).
bone cysts (1 paper, 2017). "Instead, the extensive expression of adipogenic regulator PPARγ was detected in the bone cysts." (PMID 28790361, 2017).
hepatobiliary disorder (1 paper, 2023). A non-neoplastic or neoplastic disorder that affects the liver, bile ducts, and gallbladder. "Activation of PPARγ has been linked to the occurrence of cardiac and hepatobiliary disorders." (PMID 37888725, 2023).
neoplastic disorders (1 paper, 2024). "High PPARγ expression increases cell proliferation in other neoplastic disorders." (PMID 38882990, 2024).
skin disorder (1 paper, 2022). Any deviation from the normal structure or function of the skin or subcutaneous tissue that is manifested by a characteristic set of symptoms and signs. "Therefore, PPARγ agonists may represent a promising new therapeutic strategy in the treatment of EGFRI-related skin disorders." (PMID 35324426, 2022).
PPARG also shares sentences with these, for which no sentence is quoted: acute myocardial infarction (8 papers); hypertrophy (6); stomach cancer (6); Alcohol (5); arteriosclerosis (5); lichen planopilaris (5); neurotoxicity (5); renal cell carcinoma (5); Anorexia (4); chronic periodontitis (4); complication (4); insulinoma (4); Osteopenia (4); papillary carcinoma (4); portal hypertension (4); schistosomiasis (4); thrombosis (4); arrhythmogenic right ventricular cardiomyopathy (3); Cholestatic liver disease (3); chronic lung disease (3); cicatricial alopecia (3); coronary atherosclerosis (3); diffuse large B-cell lymphoma (3); Dunnigan syndrome (3); erectile dysfunction (3); fibrosarcoma (3); hypertensive nephropathy (3); intestinal inflammation (3); intrahepatic cholangiocarcinoma (3); ischemia reperfusion injury (3).
A further 280 diseases each share a sentence with PPARG in 3 papers or fewer.